IL10 (interleukin 10)
Diseases named in the same sentence as IL10 in open-access papers (continued):
Sharing a sentence is not in itself a finding about the gene and the disease.
Hydrocephalus (6 papers, 2020 to 2025). Hydrocephalus is an active distension of the ventricular system of the brain resulting from inadequate passage of CSF from its point of production within the cerebral ventricles to its point of absorption into the systemic circulation. "In conclusion, USSCs exerted anti-inflammatory effects by suppressing both TGF-β specific isoforms, CTGF and MMP-9, recovered IL-10, restored aquaporins expression towards baseline, and reduced hydrocephalus." (PMID 33897371, 2021). "Future investigations such as the addition of supplemental MMP-9 and/or IL-10, or the addition of pharmaceuticals counteracting IL-6 and IL-8, could help in understanding if the severity of hydrocephalus can be reversed, paused or mitigated." (PMID 33514409, 2021). "Therefore, the interplay of IL-6, IL-8, IL-10, MMP-7 and MMP-9 is worth future investigations to improve our understanding of the molecular and cellular events driving hydrocephalus." (PMID 33514409, 2021). "We observed that ICH patients with hydrocephalus had higher levels of IL-6, IL-8, IL-10, and TNF-α in their CSF compared to those without hydrocephalus." (PMID 38167007, 2024).
idiopathic pulmonary fibrosis (6 papers, 2019 to 2024). Idiopathic pulmonary fibrosis (IPF) is a nonneoplastic pulmonary disease that is characterized by the formation of scar tissue within the lungs in the absence of any known cause. "Meanwhile another study found that abnormally serum sialidase NEU3 level promoted fibrosis through serum amyloid P (SAP) desialylation acceleration and IL-10 accumulation by PBMC in idiopathic pulmonary fibrosis (IPF) patients." (PMID 38500102, 2024). "Human alveolar macrophages (AMs) express high levels of interleukin (IL)-10, IL-13, and platelet derived growth factor (PDGF) in patients with idiopathic pulmonary fibrosis (IPF) and SSc." (PMID 35729674, 2022).
infectious colitis (6 papers, 2012 to 2025). A viral or bacterial infectious process affecting the large intestine. "Our experiments in the Il10-deficient mouse model of non-infectious colitis mirror this inflammation-associated increase in luminal lactate." (PMID 36434690, 2022). "At30 days PI, both groups of mice demonstrated elevated IL-10 and FOXP3 mRNA(for both P < 0.05), indicating the resolution phase ofthe infectious colitis." (PMID 22694805, 2012). "A significant increase in IL‐10 protein expression was found for infectious colitis compared to colonic mucosa in controls (p = .050), but not for colonic CD (p = .22) or for UC (p = .14)." (PMID 36169258, 2022).
insomnia (6 papers, 2021 to 2025). A sleep disorder characterized by difficulty in falling asleep and/or remaining asleep. "Previous studies have demonstrated that insomnia patients exhibit elevated levels of IL-6, IL-10, IL-1β, TNF-α, CRP, and other inflammatory markers." (PMID 40636389, 2025). "Chronic inflammation and oxidative stress are closely linked to insomnia, and Tai Chi can attenuate systemic inflammation by decreasing pro-inflammatory cytokines (e.g., IL-6, TNF-α) and increasing anti-inflammatory cytokines (e.g., IL-10), while enhancing antioxidant defenses." (PMID 41280447, 2025). "The median IL-6 levels in women with and without AIS score-based insomnia were 10.65 pg./mL and 14.95 pg./mL, respectively, and the median IL-10 levels in those two groups were 0.99 pg./mL and 1.04 pg./mL, respectively." (PMID 37840785, 2023). "The differences between IL-6 and IL-10 levels in women with and without insomnia were not significant." (PMID 37840785, 2023).
intervertebral disc degeneration (6 papers, 2014 to 2025). "Intervertebral disc degeneration and stenosis are also associated with changes in IL-10 levels in the lumbar ligament." (PMID 36036007, 2022). "Fifteen days after the induction of intervertebral disc degeneration, significant changes were observed, such as reduction in the expression metalloprotease-9 (MMP9) and interleukins (IL-6 and IL-10)." (PMID 26997908, 2016).
invasive breast carcinoma (6 papers, 2018 to 2024). A carcinoma that infiltrates the breast parenchyma. "The levels of sPD-L1 and IL-10 in serum were found to be significantly higher in invasive breast cancer (IBCa) patients than in breast fibroadenoma (FIBma) patients." (PMID 35935985, 2022).
laryngeal squamous cell carcinoma (6 papers, 2014 to 2024). A squamous cell carcinoma that arises from the larynx. "In the present study, the association between the IL-10 −1082/−819/−592 promoter polymorphisms, the plasma IL-10 levels and the risk of laryngeal squamous cell carcinoma (LSCC) was investigated in a prospective, case-control study." (PMID 24765208, 2014). "Geopropolis has also been found to be cytostatic towards human laryngeal epidermoid carcinoma cells and is known to stimulate tumor necrosis factor alpha (TNF-α) and interleukin-10 (IL-10) production by human monocytes." (PMID 29125569, 2017). "Moreover, serum levels of IL-10 correlate with the HNSCC stage, although its use as a biomarker for laryngeal squamous cell carcinoma has been contested in some studies." (PMID 36143043, 2022).
lepromatous leprosy (6 papers, 2012 to 2020). A chronic communicable infection which is a principal or polar form of leprosy. "T helper cells and T regulatory (Tregs) cells are the major source of IL-10 in lepromatous leprosy patients." (PMID 32849660, 2020). "The acknowledged immunosuppressive role of IL-10 in lepromatous leprosy as well as in M. leprae infected mice was also evident from its reduction at RR-onset." (PMID 26510990, 2015). "Contrarily, cytokine responses in lepromatous leprosy are mediated by the inflammation-mitigating cytokines (IL-4, IL-10 and a member of the leukocyte immunoglobulin-like subfamily of receptors dubbed LILRA-2) which inhibit TLR2/1 induce pro-inflammatory cytokine response and promote IL-10 release." (PMID 29641433, 2018).
liver dysfunction (6 papers, 2006 to 2025). "Pretreatment liver injury was an independent poor prognostic factor in newly diagnosed DLBCL patients, correlating with increased serum levels of liver dysfunction-associated cytokines IL-2R, IL-6, IL-10, and TNF-α." (PMID 29109622, 2017). "In the liver dysfunction group, patients had significantly higher level of IL-2R, IL-6, IL-10, and TNF-α, when compared with those in the normal liver function group." (PMID 29109622, 2017). "Of note, patients in the liver dysfunction group retained significantly higher levels of serum cytokines IL-2R, IL-6, IL-10, and TNF-α, compared with those in the matched control group (p = 0.003, p = 0.022, p = 0.045, and p < 0.001, resp.) and healthy volunteers (all p < 0.001)." (PMID 29109622, 2017). "We could not demonstrate correlations between serum levels of any cytokine and APACHE II or SOFA score, but interestingly, both IL-10 and sTNF-αR1 correlated with Child-Pugh score, an index of liver dysfunction." (PMID 17156425, 2006). "Liver dysfunction was evident through elevated biomarkers (AST, ALT, and TBIL) and pro-inflammatory IL-6, coupled with reduced anti-inflammatory IL-10." (PMID 40563258, 2025).
malignant glioma (6 papers, 2010 to 2023). A grade III or grade IV glioma arising from the central nervous system. "This study showed that spontaneous IL-10 secretion and HTL epitope WT1-332-specific IL-10 secretion from PBMCs before vaccination were associated with a poor clinical prognosis in patients with recurrent malignant glioma treated with the WT1 Trio cancer vaccine." (PMID 36672344, 2023). "Our group has previously demonstrated that when cocultured with malignant glioma cells, stimulated naïve human monocytes significantly upregulate expression of IL-10." (PMID 23737783, 2013). "A third factor produced by malignant gliomas and involved in the local immunosuppression is the cytokine IL-10." (PMID 24281089, 2010). "It is particularly interesting that in the setting of malignant gliomas, IL-10 derived from TAMs exerts an overall tumorogenic and immunosuppressive effect, whereas IL-10 secreted in persistent and high levels by T-cells can produce pro-inflammatory and anti-tumor effects." (PMID 26217588, 2015). "Whether IL-10 exerts similar anti-angiogenic and anti-metastatic effects in CNS tumors is yet unknown, although in vitro data suggest that the pro-proliferative effects of IL-10 in malignant gliomas may outweigh the inhibitory effects." (PMID 26217588, 2015). "In fact, it has been known that various immunosuppressive molecules, such as TGF-β, IL-10, and prostaglandins, are highly expressed in cancers including high-grade glioma, and these molecules could inhibit the maturation of professional APCs." (PMID 23050879, 2012). "For instance, our group recently reported that in the presence of malignant glioma cells, there is nearly complete abrogation of TNF-α and a significant upregulation of IL-10 secretion by stimulated naïve human monocytes in vitro." (PMID 23737783, 2013). "Levels of IL-10 expression are higher in malignant gliomas with 87.5% of grade III and IV and only 4% of grade II tumors showing high levels of IL-10 mRNA." (PMID 24281089, 2010).
meningococcal disease (6 papers, 2006 to 2021). "Lastly innate familial patterns of leukocyte TNFα and IL10 production have been linked with risk for mortality in meningococcal disease." (PMID 23935244, 2013). "Third, the presence of IL-10 appears to partially reverse this down-regulation, adding new knowledge to the biological effects of IL-10 in meningococcal disease and possibly in other infections activating the IL-10 signaling system." (PMID 29078758, 2017). "The detrimental effects of high IL-10 induction have been further demonstrated for Klebsiella pneumoniae and meningococcal infection, and could result in reduced phagocytic and bactericidal activity in neutrophils." (PMID 31947746, 2020). "Bjerre and co-authors analysed plasma IFN-γ and IL-10 concentrations in patients with systemic meningococcal disease (Gram-negative) and patients with Gram-positive septic shock caused by S. pneumoniae or S. aureus." (PMID 26079127, 2015).
morbid obesity (6 papers, 2014 to 2026). An excess of body weight, normally defined as an individual with a body mass index greater than 35 or a body weight greater than one hundred percent of ideal body weight. "Some studies have reported effects of morbid obesity in T and B cells in adipose tissue, such as an increase of proinflammatory cytokine production by adipose-resident T cells and a decrease of IL-10 production by B cells." (PMID 35860273, 2022). "IL-10 exhibited reduced circulating levels in severe OSA patients with respect to mild OSA subjects, even between individuals showing morbid obesity." (PMID 25944984, 2015). "In fact, there was a significant negative correlation between serum IL-10 and the index of apneas/hypopneas in the morbid obesity group; in other words, our results suggest that OSA severity increases while serum levels of IL-10 decrease." (PMID 25944984, 2015).
ocular toxoplasmosis (6 papers, 2014 to 2025). Ocular toxoplasmosis is an infection in the eye caused by the parasite, Toxoplasm a gondii. "It is now known that IL-10 levels are increased in ocular toxoplasmosis, while IL-1β is associated with more severe lesions." (PMID 37894166, 2023). "This study found that a reduction in IFN-γ and an increase in IL-6 and IL-10 production was associated with protection against vertical transmission and ocular toxoplasmosis in the offspring." (PMID 33658997, 2020). "Increased IL-10 or Treg activity can reduce inflammation, as seen in acute ocular toxoplasmosis models, where IL-10 regulates inflammation." (PMID 40872907, 2025). "This study analyzed the synthesis of Interferon gamma (IFN-γ), Tumor Necrosis Factor alpha (TNF-α), and Interleukin 10 (IL-10) in chronically infected patients which developed the symptomatic disease as cerebral or ocular toxoplasmosis." (PMID 25352834, 2014). "This study was aimed to analyze the synthesis of Interferon gamma (IFN-γ), Tumor Necrosis Factor alpha (TNF-α), and Interleukin 10 (IL-10) in chronically infected patients which developed the symptomatic disease as cerebral or ocular toxoplasmosis." (PMID 25352834, 2014). "Genotype and allele distribution for IL1β –511 and IL10 –1082 polymorphisms in individuals infected by Toxoplasma gondii with and without ocular toxoplasmosis and in individuals without the infection." (PMID 38983057, 2023).
Pain (6 papers, 2014 to 2025). An unpleasant sensory and emotional experience associated with actual or potential tissue damage, or described in terms of such damage. "It is known that serum levels of proinflammatory cytokines such as IL-1β, IL-6, and TNF-α are significantly upregulated during chronic neuropathic pain and anti-inflammatory cytokines such as IL-10 are significantly downregulated during chronic neuropathic pain state." (PMID 30755780, 2019). "The most relevant cytokines observed in PTX-induced neuropathic pain are IL-1β, IL-8, and TNF-α, as well as IL-6, IL-4, and IL-10." (PMID 40006070, 2025).
pemphigus vulgaris (6 papers, 2018 to 2026). Pemphigus is a group of chronic autoimmune skin diseases characterized by blister formations on the outer layer of the skin and the mucous membranes. "More evidence for a role of IL-10 comes from an association between genetic variants/haplotypes of IL-10 and the occurrence of pemphigus vulgaris in patients from Argentina and Slovakia." (PMID 33584677, 2020). "MuSK myasthenia gravis patients with HLA-DRB1*14 presented with increased serum levels of IgG4 autoantibodies and IL-10 concentrations, and IL-10 also plays a role in animal models of pemphigus vulgaris and MuSK myasthenia gravis." (PMID 35095860, 2021).
polyarthritis (6 papers, 2012 to 2024). "M2 polarization was constantly deficient from the onset of polyarthritis as indicated by impaired expression of Ppar-γ, Arg-1 and Il-10." (PMID 35111160, 2021). "Their findings confirm an association between the “low” IL-10–producing haplotype and disease severity in children with oligoarticular-onset JIA that extends to polyarthritis." (PMID 28257625, 2017). "In order to unravel the relative contribution of endogenous B cell derived IL-10 in a polyarthritis model, we generated mixed bone marrow chimera mice with IL-10 knocked-out specifically on B cells." (PMID 22315945, 2012). "Although the number of ERA patients included in our study was very low, it stands out that IL-10 is differently regulated in ERA compared to oligoarthritis and polyarthritis." (PMID 39125893, 2024). "Of the three subgroups presented, polyarthritis patients had the highest concentration of serum IL-6 (264.24 pg/mL; IQR 9706.65) and ERA patients the highest concentration of serum IL-10 (30.87 pg/mL; IQR 51.27)." (PMID 39125893, 2024). "A substantial (p < 0.0001) downregulation in IL-4,-10, and I-κBα expression in the diseased control group (IL-4: 31.27 ± 1.12%, IL-10: 37.09 ± 0.9%, I-κBα: 55.24 ± 1.04%) in comparison to normal group in CFA induced polyarthritis." (PMID 36234860, 2022). "Treatment with either ASMA or ATSA attenuated the progression of clinical features of polyarthritis, improved gait and body weight gain, reduced the elevated serum IL-17 and further increased both IFN-γ and IL-10." (PMID 27802332, 2016). "Next we wanted to elucidate and validate the role of IL-10 secreting Bregs in CIA, a polyarthritis model involving both severe inflammation and cartilage and bone erosion." (PMID 22315945, 2012). "The most significant difference was related to IL-10 rs1800896 and rs1800872/rs1800871, where there was high evidence of LD between the SNPs in the polyarthritis group but not in the oligoarthritis group." (PMID 39125893, 2024).
primary immunodeficiency (6 papers, 2017 to 2022). "Neonatal or infantile-onset IBD is often associated with primary immune deficiency disorders, especially those caused by mutations in IL-10, XIAP, NCF2, IPEX, and TTC7A." (PMID 35783276, 2022). "IBD-like monogenic disorders are related to primary immunodeficiency, for example, defects of T and B lymphocyte selection and activation, disorders affecting regulatory T cell activity, and interleukin 10 (IL10) and IL10 receptor A/B (IL10R) A/B signaling." (PMID 33643966, 2020).
prostatitis (6 papers, 2013 to 2025). An infectious or non-infectious inflammatory process affecting the prostate gland. "In sum, our findings suggested that IL-10 gene -592A>C polymorphism may represent a promising candidate locus for the occurrence of PCa, and further signified a contributing role of this polymorphism in prostate carcinogenesis." (PMID 28526808, 2017). "Inflammatory cytokines, particularly TNF-α and IL-10, are elevated in prostatitis, and their presence has been detected in the urine of prostatitis patients." (PMID 38258089, 2024). "Mechanistically, PARP1 promote the NF-κB expression, which could regulate downstream inflammatory cytokines, including IL-6, IL-10, IL-12p70, CCL2, IFN-γ in M1 macrophages, leading to the accumulation of proinflammation factors and ultimately exacerbating prostatitis." (PMID 40032778, 2025). "Additionally, the expression of IL-6, IL-12p70, CCL2 and TNF in the Parp1−/− model group was markedly reduced and IL-10 increased significantly compared to that in the WT model group, suggesting that PARP1 enhanced the inflammatory factors secretion in prostatitis." (PMID 40032778, 2025).
rectal cancer (6 papers, 2019 to 2025). A primary or metastatic malignant neoplasm that affects the rectum. "In the experimental mouse model, E. faecalis can induce intestinal inflammation, dysplasia and, rectal carcinoma in IL-10 knock-out mice." (PMID 33352792, 2020). "In addition to SMAD7 (P = 0.0005) and SMAD3 (P = 0.0003), several other genes or genetic regions (CYP2R1, CHAF1A, CREBBP, IL10, SNPs identified in genome-wide association studies (GWAS) to be associated with IGF levels, IGFBP2/IGFBP5, IGFBP3, and C-MYC region) were associated with rectal cancer." (PMID 31434255, 2019).
renal dysfunction (6 papers, 2012 to 2024). "In previous works, IL-10 level was also found to be significantly increased in patients who suffered from postoperative renal dysfunction, which was characterized by creatinine level raised above 176 μmol/L." (PMID 22529517, 2012). "Similarly, heightened IL-10 levels in cases of renal dysfunction are predictive of mortality in acute circumstances." (PMID 38921319, 2024). "Similarly, raised IL-10 levels in renal dysfunction predict mortality in the acute setting." (PMID 28747177, 2017). "The growth and decay of serum creatinine, which is elevated during renal dysfunction, occurred on a time scale that parallels Group A [TNF-α, IL1, and IL10] response." (PMID 23049677, 2012). "In this work, the highest levels of IL-6, CCL2 gene expression and IL-10 release and the lowest transcript levels of CCR2, which reflects monocyte maturation, have been observed after treatment with IS at concentrations found in subjects with moderate renal dysfunction." (PMID 26925780, 2016).
salmonellosis (6 papers, 2013 to 2025). Infections with bacteria of the genus salmonella. "Pro-inflammatory cytokines like TNFα and IL-1β, and anti-inflammatory IL-10 play an important role in the pathophysiological processes occurring in porcine salmonellosis caused by S. Choleraesuis." (PMID 35436975, 2022). "Our results demonstrated an interesting difference in IL-10 levels among the salmonellosis and post-salmonellosis cohorts that differed in autoantibody levels." (PMID 31277323, 2019). "The concentration of systemic IL-10 in patients with salmonellosis is significantly higher compared to control subjects." (PMID 26904722, 2013). "The levels of IL-10 and IFN-γ was also determined in salmonellosis patients with a normal level of autoantibodies: S. Enteritidis-infected (IL-10 in 19 patients and IFN-γ in 17 patients), S. Typhimurium-infected (n = 2 for both IL10 and IFN-γ), and the control group (n = 13)." (PMID 31277323, 2019).